MCL1 (MCL1 apoptosis regulator, BCL2 family member)
Diseases named in the same sentence as MCL1 in open-access papers (continued):
Sharing a sentence is not in itself a finding about the gene and the disease.
cancer (continued). "Deletion of FBXW7 leads to the accumulation of the pro-survival factor MCL-1, which confers chemoresistance to cancer cells." (PMID 38027013, 2023). "MCL1 gene amplification is frequently found in human cancers, including high incidences in lung and breast cancers." (PMID 37880389, 2023). "S63845 selectively killed cancer cells, which relied on MCL-1 for survival, by activating the BAX/BAK-dependent mitochondrial apoptotic pathway, confirming its on-target effects." (PMID 37108344, 2023). "Certain medications that inhibit gene transcription in cancer cells exert their deadly effects on other cells, in part, by downregulating MCL-1." (PMID 37111571, 2023). "Frequent overexpression of Mcl-1 in various human tumors is recognized as a defense mechanism for cancer cells to evade apoptosis." (PMID 37537243, 2023). "To investigate the role of Mcl-1 in regulating the life and death of cancer cells, we carried out shRNA knockdown, inhibition and overexpression experiments in MCF-7 cells." (PMID 37537243, 2023). "MCL1 is an anti‐apoptotic BCL2 family member that is often overexpressed in various malignant tumors." (PMID 36653904, 2023). "Recently, MCL1 has been a potent anti-apoptotic protein that plays a critical role in cell survival and drug resistance in various cancers." (PMID 37407915, 2023). "Knockdown of Mcl-1 with RNAi technology resulted in induced apoptosis and reduced growth of cancer cell lines." (PMID 37736508, 2023). "Of note, the downregulation of MCL-1 levels restores the effectiveness of these anti-cancer drugs in several cancer cell lines." (PMID 36342579, 2023). "Targeting MCL1 represents a promising therapeutic approach for overcoming resistance to cancer treatment and improving patient outcomes." (PMID 37744271, 2023). "MCL1 is a potent anti-apoptotic protein that plays a critical role in cell survival and drug resistance in various cancers." (PMID 37407915, 2023). "MYC and MCL1 mRNA downregulation has been described previously from the blood of patients treated with enitociclib during dose escalation and across many cancer indications including NHL and solid tumors using a qPCR clinical trial assay." (PMID 37882668, 2023). "The pro-survival members BCL-2 and myeloid leukemia 1 (MCL-1) have long been attractive targets because they are upregulated in diverse cancer types and confer drug resistance." (PMID 37919300, 2023). "MCL-1 plays a crucial role in the process of guaranteeing cell survival and is usually shown to be genetically elevated in human cancers." (PMID 37111571, 2023). "Among the five antiapoptotic genes, three (BCL2, BCL2A1, and MCL1) can be regulated by NF-κB in different types of cancer cells." (PMID 36853387, 2023). "In cancer cells or genetically engineered cells dependent on MCL-1 for cell survival, BAPTAi (and TF-BAPTAi) induced significant cell death, regardless of intracellular Ca2+ buffering." (PMID 37684238, 2023). "They found that Maritoclax induces caspase-3 activation by directly binding to Mcl-1 and targeting it for proteasomal degradation and sensitizes cancer cells to ABT-737." (PMID 36986514, 2023). "When 3000 samples from 26 different cancers were profiled, the Mcl-1 and BCL-2A1 genes were among the most amplified genes." (PMID 37601693, 2023). "Mcl-1 is an antiapoptotic protein in the Bcl-2 family that is essential for the survival of multiple cell lineages and is highly amplified in human cancer." (PMID 38239638, 2023). "These compounds were capable of forming dendriplexes by promoting the entrance of Mcl-1-FITC (myeloid cell leukemia-1 fluorescein labelled) small interfering RNA (siRNA) to HEPG2 cancer cells, protecting the siRNA from RNAse." (PMID 36830276, 2023). "Since we started this study, newer more potent MCL-1 specific inhibitors have been developed and advanced to clinical studies as cancer therapeutics, including S64315/MIK665 (a derivate of S63845), AMG 176, and AZD5991." (PMID 37864894, 2023).
cancer (continued). "Several studies have shown that targeting MCL1 can induce apoptosis in cancer cells and sensitize them to chemotherapy." (PMID 37744271, 2023). "In line with this, inhibition of the PI3K/Akt signaling pathway resulted in increased sensitivity of cancer cells to SA accompanied by attenuating SA-induced Bcl-xL and Mcl-1 gene expressions." (PMID 37696858, 2023). "Despite these differences, BAPTAi and TF-BAPTAi were equally potent in inducing the death of MCL-1-addicted cancer cells." (PMID 37684238, 2023). "Given the increased expression of c-Myc in T-PLL, and the role of CDK9 in Myc-addicted cancers, in conjunction with the Mcl-1 dependence observed in a subset of T-PLL, CDK9 inhibition is an attractive and highly rational approach." (PMID 37569479, 2023). "In particular, PTBP1 regulates several pathways that play a key role in cancer growth and survival by modulating apoptosis and proliferation through alternative splicing of MCL1 and ADAR1." (PMID 36949664, 2023). "Expression of the MCL-1 gene increases significantly after treatment with BH3 mimetics, causing the cancer cell to form a specific bypass that omits the blocked proteins." (PMID 36902139, 2023). "Due to their known regulatory effects on cell death, anti-apoptotic members Bcl-2, Bcl-xL and Mcl-1 are of importance in cancer therapy as they prevent cell termination in cancer cells and promote the survival of these cancer cells." (PMID 37686541, 2023). "ABT-263, an orally available, selective inhibitor of the anti-apoptotic BCL-2 family proteins, including Bcl-2, Bcl-XL, and Mcl-1, has been demonstrated to possess antitumor activity against various types of cancers and is in clinical trials." (PMID 37063257, 2023). "BH3 mimetic antagonists of other antiapoptotic proteins have also been developed as A-1155463 and A-1331852 for Bcl-xL or S63845, AMG 176, for Mcl-1 in cancer." (PMID 36982637, 2023). "MCL1 is highly expressed in different malignancies and reduced MCL1 expression in cells promotes apoptosis, inhibits cancer cell proliferation, along with cell cycle arrest." (PMID 36984512, 2023). "For example, one of the protooncogenic functions of USP9X stems from its interaction with the anti-apoptotic protein Mcl-1, which promotes the increased expression of Mcl-1 in cancer tissues and inhibits apoptosis 31,32." (PMID 37057289, 2023). "Since BCL-XL inhibition has been shown to increase MCL-1 levels in some cancer cell lines as a compensatory mechanism." (PMID 36588105, 2023). "Mcl-1 appears to be a key factor for the resistance to conventional cancer therapies in some cancer types." (PMID 37371761, 2023). "The targeted MCL-1 inhibitor molecule S63845 is proving to be effective and safe in many types of cancer." (PMID 36902139, 2023). "MCL-1 is overexpressed in several cancers and mediates resistance to apoptosis triggered by chemotherapy and targeted therapy." (PMID 37601693, 2023). "Inhibition of BMI-1 also leads to DUB3-dependent Mcl-1 degradation, resulting in enhanced apoptosis of cancer cells." (PMID 37259388, 2023). "In this study, we find that Taxol-induced mitotic block in cancer cells is partly controlled by TRIP12 via its positive regulation of MCL-1 protein." (PMID 36672454, 2023). "The apoptosis assay also confirmed the increased cancer cell death via the Mcl-1 nioplex/TZ dual treatment, which proceeded to late apoptosis/necrosis after 24 h of treatment." (PMID 37896184, 2023). "Switching from antiapoptotic to proapoptotic MCL-1 protein by controlling MCL-1 splicing appears to be a promising strategy in cancer therapy." (PMID 37601693, 2023). "Myeloid cell leukemia 1 (Mcl‐1), a prosurvival Bcl‐2 protein, is commonly overexpressed in cancers that affect humans." (PMID 37970406, 2023). "Researchers have tested BH3-mimetic drugs in preclinical cancer models, and some drugs that target MCL-1 and BCL-XL have been assessed in phase I clinical trials for certain cancers." (PMID 37564206, 2023).
cancer (continued). "Concerning S63845, it has been reported that this BH3 mimetic is able to kill MCL‐1‐dependent cancer cells in vitro, including leukemia, lymphomas and MM cells and it synergized with ABT‐199 in T‐cell acute lymphoblastic leukemia (T‐ALL)." (PMID 37704591, 2023). "Meayamycin D induced alternative splicing of MCL-1, showed strong synergism with venetoclax in drug-resistantlung cancer cells, and was cancer-specific over normal cells." (PMID 37870431, 2023). "Only the gene MCL1 (at position 57 in the ranking) was classified as a cancer target in the CTD2 database." (PMID 36838660, 2023). "Our findings were similar to those of previous studies that showed PROK-1 induced Akt phosphorylation, upregulated the Bcl-2 family member Mcl-1, and acted as an anti-apoptotic effector in cancer cells." (PMID 37070074, 2023). "The previously discussed anti-apoptotic gene products, Bcl-2, Bcl-xL, Mcl-1 and survivin, have been found to be overexpressed in several human cancers." (PMID 37686541, 2023). "Lastly, the expression of Mcl-1, a prominent target in cancer therapy, a member of the anti-apoptotic BCL-2 family, and a predictor of poor prognosis and disease recurrence in AML, was impacted by the inhibitor combination." (PMID 36980769, 2023). "In summary, the MCL1 gene plays a critical role in cancer by promoting cell survival and resistance to chemotherapy." (PMID 37744271, 2023). "Mcl-1 is an antiapoptotic, B-cell lymphoma (BCL)-2 family protein whose high expression has been associated with increased cancer cell survival that translates to chemotherapy resistance and poor patient prognoses." (PMID 37537243, 2023). "The overexpression of induced myeloid leukemia cell differentiation protein (Mcl-1), a member of anti-apoptotic Bcl-2 family proteins, is seen in a range of human cancers." (PMID 36984785, 2023). "MCL-1 is known to be important for the sustained growth of several cancers and BH3-mimetic drugs targeting MCL-1 are currently in clinical trials for select blood cancers." (PMID 37567974, 2023). "We therefore sought to determine if emerging anti-cancer drugs that target MCL1 combine with cisplatin in a synergistic fashion." (PMID 37760451, 2023). "Myeloid cell leukemia-1 (Mcl-1) is a crucial anti-apoptotic member of the Bcl-2 protein family that contributes significantly to the development of various human cancers." (PMID 37669923, 2023). "DDX5 is an upstream master regulator in cancer and positively controls the expression of survivin, Mcl-1, XIAP, and cIAP2." (PMID 36771042, 2023). "The overexpression of MCL-1 is described in several human cancers such as non-small cell lung cancer, breast cancer, ovarian cancer and pancreatic cancer." (PMID 37511133, 2023). "The small molecule S63845 specifically binds to the BH3-binding domain of Mcl-1, and thus can kill Mcl-1-dependent cancer cells by activating Bax/Bak-dependent apoptosis pathways." (PMID 36902392, 2023). "Gossypol acetic acid, a polyphenolic compound isolated form cottonseeds, has been reported to inhibit Bcl-2, Bcl-xL and Mcl-1 function and have antiproliferative effects on some cancer cells in vitro." (PMID 37112871, 2023). "The major anti-apoptotic Bcl-2 family members including Bcl-2, Mcl-1 and Bcl-xL have been observed to be overexpressed in various cancer cells, which confer cancer cell resistance to apoptosis." (PMID 36658493, 2023). "Top-scoring regulators of apoptosis, CASP8, BAX, and MCL1, indicated the mode of cell death induced by IFN-γ, and support the association of CASP8 mutations with immune evasion in TCGA pan-cancer analyses." (PMID 36669486, 2023). "Considering the potential therapeutic applications of MCL-1 inhibitors, a safe therapeutic window in cancer patients is suggested to be achievable, regardless of the pleiotropic functions of MCL-1." (PMID 37835493, 2023). "The discovery of MI-238 provides a novel drug candidate to target Mcl-1 for future cancer treatment." (PMID 36658493, 2023).
cancer (continued). "This study offers valuable insights into the development of novel Mcl-1 inhibitors for cancer therapy." (PMID 37669923, 2023). "STAT3 activation contributes to the expression of antiapoptosis proteins, such as Bcl-xL and Mcl-1, thus decreasing natural apoptotic cell death and favouring cancer cell growth." (PMID 37298475, 2023). "Since safety and activity studies are underway in cancer clinics for MCL-1 and BCL-2 inhibitors, we expect that re-purposing them for TB treatment should translate more readily and rapidly to the clinic." (PMID 37864894, 2023). "Consistent with this statement, it has been shown that, in xenograft models, knockdown of MCL-1 decreased the proliferation rate of cancer cells to a greater degree than that seen in controls." (PMID 37601693, 2023). "The upregulation of several prosurvival and antiapoptotic proteins (e.g., c-Myc, Mcl-1, and survivin) in cancer cells has been confirmed to contribute to their overproliferation and resistance to apoptosis." (PMID 35088192, 2023). "Firstly, the direct inhibition of PFKFB3 emerges as a key regulator of mTORC1 activity and a promising target in MCL-1-dependent cancers." (PMID 37684238, 2023). "In a large scale cancer genome study, MCL1 was found to be one of the most frequently amplified genes in cancers." (PMID 36329234, 2023). "As a member of the Bcl-2 family, overexpression of Mcl-1 in cancer cells disrupts the balance between antiapoptotic and pro-apoptotic proteins, leading to a malignant proliferation of tumors." (PMID 37259388, 2023). "Laboratory cell line data, murine model systems, and clinical observations clearly underscore MCL-1 as a therapeutic target for many cancers." (PMID 37601693, 2023). "Vincristine exhibits anti-cancer effects by enhancing cell apoptosis, while HMGB1 exhibits the opposite role by upregulating the anti-apoptotic myeloid leukemia 1 (MCL-1) protein levels, thus contributing to the autophagy-mediated protection of cancer cells." (PMID 37511951, 2023). "Since this work, newer more potent MCL-1 inhibitors have been reported, including ones with efficacy in mouse cancer models." (PMID 37864894, 2023). "Alternatively, small molecule inhibitors of MCL-1 can be exploited against cancer and chemotherapy resistance." (PMID 36672454, 2023). "Studies with some cancer cells also demonstrate that the ability of ouabain to initiate apoptosis correlates with reduced expression of the anti-apoptotic proteins Mcl-1, Bcl-XL, and Bcl-2, or increased expression of the pro-apoptotic proteins Bid and Bax." (PMID 36830836, 2023). "NOXA acts as a pro-apoptotic protein by inhibiting the anti-apoptotic protein MCL-1 in various cancer cell lines." (PMID 38039297, 2023). "All together, these data suggest that MCL1 inhibition leads to a reduction in cancer stemness in this cellular model." (PMID 37446326, 2023). "Elevated expression levels of MCL1 prevents cancer cells from initiating apoptosis in the face of many intrinsic tumor-suppressing pathways and extrinsic therapeutic treatments aimed at controlling tumorigenesis." (PMID 37407915, 2023). "The combination of TZ and Mcl-1 inhibitors results in a synergistic effect and a more comprehensive and potent approach to cancer treatment." (PMID 37896184, 2023). "Cancer cells can have increased levels of MCL-1, a protein that helps cells survive and prevents apoptosis." (PMID 37880389, 2023). "Amplification was relatively higher in breast and non-small cell lung cancer (NSCLC) than in the other types of cancer and was correlated with higher amounts of Mcl-1 messenger RNA (mRNA) and unfavorable overall survival in patients." (PMID 37601693, 2023).
cancer (continued). "Melatonin regulated the protein expressions of the HIF-1α and Bcl2 pathways’ downstream proteins, including MCL1, Bcl-XL, Bax, claspin, and survivin, which possess anti-cancer effects in numerous cancer cell types." (PMID 37086261, 2023). "In light of the importance of Mcl-1 in cancer cell survival, developing Mcl-1 inhibitors have been extensively studied and a number of Mcl-1 inhibitors have been developed." (PMID 36658493, 2023). "As CSCs help cancer cells to survive, these findings support the innovation of cancer treatments and the ongoing development of RT derivatives as a new compound that not only targets Mcl-1 but also inhibits CSCs by Akt suppression." (PMID 36982418, 2023). "Approximately 12% of human cancers of diverse origin carry somatically acquired amplifications of the region that harbours the MCL-1 gene." (PMID 36342579, 2023). "Bonneaud and colleagues unraveled that targeting MCL-1 via BH3 mimetic, an antagonist to various BCL-2 congeners, including MCL-1, can mitigate the invasion of cancer cells and inhibit their tumor-promoting function." (PMID 37784082, 2023). "Most of the down-regulated hub proteins (ESR1, MCL1, LCK, TBP, and PCNA) play roles in the proliferation or survival of cancer cells, and CHEK1 is associated with the cell cycle checkpoint in cancer cells." (PMID 35563525, 2022). "Taken together, these results show that ONG41008 induced cellular senescence in cancer cells followed by senolysis via heavy G2/M arrest, mitotic collapse, multinucleation, and induction of Mcl1." (PMID 35743290, 2022). "Performing this approach, we identified two inhibitors showing high affinity for recombinant Bcl-2, Bcl-xL and Mcl-1 proteins and in vitro/in vivo anti-tumoral activity in preclinical cancer models with different histotype." (PMID 35265218, 2022). "F-box and WD repeat domain-containing protein 7 (FBW7), as a key component of UPS proteins and a critical tumor suppressor in human cancers, controls proteasome-mediated degradation by ubiquitinating oncoproteins such as c-Myc, Mcl-1, cyclin E, and Notch." (PMID 36457505, 2022). "We also identified higher levels of bax and mcl1 mRNA levels in leukocytes compared to cancer cells, and in other stromal cells (fibroblasts) compared to cancer cells (ANOVA p ≤ 0.01, Tukey post-hoc p < 0.01)." (PMID 34754079, 2022). "Overexpression of Mcl-1 is an important reason for the resistance to various cancer therapies, including radio- and chemotherapies." (PMID 35301297, 2022). "Although Mcl-1 was described as an oncogene in many cancers, to date, limited knowledge is available about the role of Mcl-1 in the tumorigenesis of BC." (PMID 35783514, 2022). "Recently, it has been shown that Mcl-1 is also well known as a miR-153 target gene in inhibiting metastasis in some types of cancer, including oral and liver cancer." (PMID 36158686, 2022). "A series of deubiquitinases (DUBs) functionally oppose E3 ligases by removing ubiquitin chains and have been reported to stabilize MCL-1 in a range of cancer types." (PMID 35349392, 2022). "MCL1 has been proved to be overexpressed in many human cancers and contributes to cancer occurrence and inhibits apoptosis." (PMID 36262872, 2022). "Sp1, a transcription factor that binds to the Mcl-1 promoter region, has already been tested and found to play important physiological roles, such as in apoptosis, by targeting Mcl-1 in cancer." (PMID 35524332, 2022). "Somatic copy number alteration studies in many cancers identified Mcl-1 as the topmost genes with increased copy number." (PMID 35273915, 2022). "In our study, we examined an additional role for MCL-1 in irradiation-induced cancer stem-like cells and acquired radioresistance in NPC." (PMID 35136016, 2022). "Mcl-1 has an important role in tumor formation; most cancer cells, therefore, need to maintain Mcl-1 expression and its stability." (PMID 35745769, 2022).